RNU6-881P (RNA, U6 small nuclear 881, pseudogene)
Gene: Small nuclear RNA gene on chromosome 9 (131,126,990 to 131,127,091, forward strand). Ensembl gene ENSG00000252622.
Homologues: Orthologues: chimpanzee U6 (98% identical), macaque U6 (95% identical), dog U6 (77% identical), guinea pig U6 (76% identical), rabbit U6 (75% identical), mouse Gm24836 (72% identical), mouse Gm24374 (68% identical), pig U6 (68% identical). Paralogues in human: RNU6-767P (83% identical), RNU6-24P (82% identical), RNU6-560P (82% identical), RNU6-1311P (81% identical), RNU6-19P (81% identical), RNU6-43P (81% identical), RNU6-737P (81% identical), RNU6-1024P (80% identical), RNU6-1091P (80% identical), RNU6-1209P (80% identical), RNU6-1316P (80% identical), RNU6-1340P (80% identical), and 1284 more.